KCNQ1 (potassium voltage-gated channel subfamily Q member 1)
Diseases named in the same sentence as KCNQ1 in open-access papers (continued):
Sharing a sentence is not in itself a finding about the gene and the disease.
cancer (continued). "Furthermore, we employed a Cancer Cell Line Encyclopedia (CCLE) analysis to further verify the effect of KCNQ1 expression levels on drug sensitivity in cancer cell lines." (PMID 35216393, 2022). "The cancer phenotype in KCNQ1 mutant hamsters was unique in several aspects." (PMID 35954238, 2022). "Finally, we employed the genomics of a Drug Sensitivity in Cancer (GDSC)-based analysis to identify lapatinib as a potential candidate for the treatment of LUAD in the context of low KCNQ1 expression." (PMID 35216393, 2022). "How these cancers arise in KCNQ1 KO hamsters is an area of active investigation." (PMID 35954238, 2022). "To verify whether KCNQ1 has a broad value, we investigated differential expression across cancers and confirmed the prognostic value by means of a Kaplan–Meier analysis." (PMID 35216393, 2022). "Similarly, KCNQ1 KO hamsters developed a wide range of lethal cancers while Kcnq1 KO mice fail to develop cancers at all." (PMID 35954238, 2022). "There is also evidence that the reduction in KCNQ1 expression in cancer cells may be mediated by promoter hypermethylation." (PMID 31149338, 2019). "With a view to exploring possible pharmaceutical approaches that could effectively target LUAD, we utilized the Genomics of Drug Sensitivity in Cancer (GDSC) repository of Q-omics analyses to identify drugs that feature potentiation effects in the context of low KCNQ1 expression." (PMID 35216393, 2022). "The protein levels of SCN5A and KCND3 decreased and SCN10A and KCNQ1 increased, similar to the levels in AGS and SW480 cancer cell media treated cells." (PMID 35265687, 2022). "Furthermore, we have previously identified that KCNQ1 and KCNQ3 RNA expression correlates with a cancer gene expression profile." (PMID 37748809, 2023). "In addition, the expression patterns of KCNQ1 lacked tissue specificity and did not demonstrate a similar expression tendency among pan-cancers and their corresponding adjacent normal tissues (available online)." (PMID 38807370, 2024). "Similarly, humans who are mutant for KCNQ1 do not develop cancer, aside from the development of gastric hyperplasia which can represent a premalignant stage of gastric cancer." (PMID 35954238, 2022). "Furthermore, after using 3-Methyladenine (3-MA), an inhibitor of PI3K, the increased levels of phosphorylated PI3K and Akt were decreased, and DNMT3A, DNMT3B, KCND3, and KCNQ1 levels were also rescued compared with AGS and SW480 cancer cell media treated cardiomyocytes." (PMID 35265687, 2022).
cardiovascular diseases (15 papers, 2014 to 2024). "The levels of the potassium channel protein KvLQT1 (encoded by the gene KCNQ1) decline with aging and age-related cardiovascular disease." (PMID 25543668, 2014). "In addition, several ion channels are modulated by STS and its precursor Tanshinone IIA in some cardiovascular disease models, such as human cardiac KCNQ1/KCNE1 (I-Ks) K+ channels, high conductance Ca2+ activated K+ channels (BKCa), KV2.1 and KV1.5." (PMID 28542554, 2017). "Furthermore, no critical nucleotide substitutions for cardiovascular diseases, such as KCNQ1, KCNH2 and SCN5A, were found in the comprehensive NGS analysis." (PMID 35486589, 2022).
heart disease (11 papers, 2015 to 2025). "One of the first cardiac-disease hiPSC models was generated from LQT1 (a type of LQTS) patients with a missense mutation (R190Q) in KCNQ1, which encodes a voltage-gated potassium ion channel." (PMID 28883014, 2017). "Several wrongly classified genes were associated with inherited cardiac diseases, such as SCN5A, KCNQ1, and RYR2, which renders the tissues less suitable for reliable gene expression examinations in relation to cardiac disease." (PMID 40373069, 2025). "Furthermore, several studies have confirmed that KCNQ1 dysfunction can cause SSS and other heart diseases, such as long QT interval syndrome and abnormal internode conduction." (PMID 39723092, 2024). "In addition, the human KCNQ1/KCNE1 channel, closely related to heart disease, was shortage of potent peptide blocker until now." (PMID 29925780, 2018).
infection (5 papers, 2013 to 2025). The state of being infected such as from the introduction of a foreign agent such as serum, vaccine, antigenic substance or organism. "As for cells with the 1:1 infection ratio, KCNQ1-GFP localized at the sarcolemmal membrane in unstimulated cells." (PMID 32833978, 2020). "In addition to the immunofluorescent staining, the transcriptional analysis of parietal cell markers shows that ATP4A and AQP4 were significantly down regulated following a trickle infection, whereas KCNQ1 transcript levels were unchanged in all animals." (PMID 24330735, 2013). "After infection and adenoviral expression of AC9-D399A for 48 h, cells were stimulated with 1 μM isoproterenol for 5 min and then assayed by immunoprecipitation of Yotiao followed by western blotting for PKA phosphorylation of Ser-27 of KCNQ1 versus total KCNQ1." (PMID 31461851, 2019).
metabolic disease (4 papers, 2017 to 2025). A congenital disorder (due to inherited enzyme abnormality) or acquired (due to failure of a metabolically important organ) disorder resulting from an abnormal metabolic process. "Our findings show a correlation between two KCNQ1 sites and body fat percentage, further support the emerging role of this gene in metabolic diseases." (PMID 41007833, 2025). "Pyrosequencing analyses were performed for the candidate genes KCNJ11, PPARγ, PDK4, KCNQ1, SCD1, PDX1, FTO and PEG3 in peripheral blood leukocytes (PBLs) from 25 patients diagnosed with only T2D, 9 patients diagnosed with T2D and MetS and 11 control subjects without any metabolic disorders." (PMID 28727822, 2017).
hematologic malignancies (1 paper, 2025). "Notably, several drug-gene pairs—including those targeting CASP8, CASP10, KCNQ1, and HSPA8—are not currently approved nor under clinical evaluation for LN, representing investigational candidates with potential for future development in hematologic malignancies." (PMID 40883272, 2025).
kidney disease (1 paper, 2023). "Studies on gene-environment interactions have suggested significant genetic and environmental factors such as smoking, waist circumference, and sex for eNOS rs2070744, PPARGC1A rs8192678, KCNQ1 rs2237895, and KCNQ1 rs2283228 with kidney disease." (PMID 37187702, 2023).
myopathy (1 paper, 2021). A disease of the muscle in which the muscle fibers do not function properly. "Finally, nine rare PTVs in the ACMG59 genes were harbored by 14 carriers, two of which displayed expected phenotypes: myopathy (frameshift deletion in RYR1) and prolonged QTc interval (frameshift insertion in KCNQ1)." (PMID 34691145, 2021).
KCNQ1 also shares sentences with these, for which no sentence is quoted: cardiac arrhythmias (35 papers); autism (6); heart failure (6); hypertrophic cardiomyopathy (6); diabetic nephropathy (5); Hearing impairment (4); sick sinus syndrome (4); depression (3); familial hypercholesterolemia (3); Marfan syndrome (3); pulmonary edema (3); adenocarcinoma (2); age-related hearing loss (2); atrioventricular block (2); episodic ataxia (2); injury (2); iron deficiency anemia (2); ischaemic stroke (2); myocardial infarction (2); neurological disorders (2); non-small cell lung carcinoma (2); prostate carcinoma (2); Timothy syndrome (2); adrenocortical tumors (1); alcoholic cirrhosis (1); Alzheimer disease (1); angiosarcoma (1); aortic aneurysm (1); Ataxia (1); attention deficit-hyperactivity disorder (1).
A further 97 diseases each share a sentence with KCNQ1 in 1 paper.